KCNQ4 (potassium voltage-gated channel subfamily Q member 4)
Diseases named in the same sentence as KCNQ4 in open-access papers (continued):
Sharing a sentence is not in itself a finding about the gene and the disease.
cancer (2 papers, 2023). A tumor composed of atypical neoplastic, often pleomorphic cells that invade other tissues. "Next, we utilized UALCAN database to explore the association between KCNQ4 expression and patient outcomes in various types of cancer." (PMID 37903775, 2023). "To investigate the association of KCNQ4 with malignancy, first, we excluded the cancer types with fewer than three samples." (PMID 37903775, 2023). "The main type of KCNQ4 alteration in different types of cancers was "amplification", followed by “mutation”.The frequency of KCNQ4 alterations (> 8%) was highest in OV, where amplification was the predominant type of alteration." (PMID 37903775, 2023). "In summary, through bioinformatics analysis, the abnormal expression of KCNQ4 in pan-cancer is closely related to methylation, mutation, prognosis, heterogeneity, dryness, and immune infiltration." (PMID 37903775, 2023). "Our findings indicated a substantial correlation between KCNQ4 expression and the expression levels of immune checkpoint-associated genes in various types of cancer." (PMID 37903775, 2023). "On this basis, it would be interested to study the action mechanism of potassium channel KCNQ4 and its role in cancer." (PMID 36859185, 2023). "We also utilized the TIMER 2.0 database to verify the expression of KCNQ4 in different cancers, and the results were consistent with TCGA." (PMID 37903775, 2023). "The results from SMART analysis revealed differential methylation patterns of the KCNQ4 gene across various cancers, suggesting its potential functional implications." (PMID 37903775, 2023). "The result showed that KCNQ4 was significantly up-regulated in 6 cancers, including WT, PAAD, ALL, LAML, PCPG and CHOL, and significantly down-regulated in 25 cancers, such as GBM, GBMLGG, LGG, UCEC, BRCA and CESC." (PMID 37903775, 2023). "According to the results of our pan-cancer analysis, KCNQ4 is aberrantly expressed in a range of malignancies, but until now, most of the research on KCNQ4 has focused on non-syndromic hearing loss and less on cancer." (PMID 37903775, 2023). "In the "pan-cancer RNA-seq" module, we analyzed the correlation between KCNQ4 expression and OS in different types of cancer." (PMID 37903775, 2023). "Additionally, through the BioGPS database, we observed that KCNQ4 exhibited a low expression level in nearly all cancer cell lines." (PMID 37903775, 2023). "We presented 10 cancer cell lines with the highest KCNQ4 expression level." (PMID 37903775, 2023). "In recent years, several studies reported the role of KCNQ4 in several malignant tumors." (PMID 37903775, 2023). "Among all the cancers, SKCM had the highest frequency of KCNQ4 mutations." (PMID 37903775, 2023). "Additionally, in 11 cancer types, expression of KCNQ4 was substantially correlated with cancer staging." (PMID 37903775, 2023). "These research results provide new ideas for using KCNQ4 as a novel therapeutic target for cancer." (PMID 36859185, 2023). "Therefore, a comprehensive and systematic analysis of KCNQ4 in the context of pan-cancer is crucial." (PMID 37903775, 2023). "Additionally, the PFS curve indicated that high KCNQ4 expression was associated with adverse prognosis in GBMLGG, LGG, KIRP, KIPAN, and ACC patients, suggesting that KCNQ4 may serve as a promising prognostic marker for a variety of cancers." (PMID 37903775, 2023). "However, a pan-cancer analysis of KCNQ4 based on clinical big data has not been reported." (PMID 37903775, 2023).
psychiatric diseases (2 papers, 2017 to 2021). "KCNQ4-specific openers were hypothesized as effective drugs for the treatment of psychiatric diseases." (PMID 34381336, 2021).
adenocarcinoma (1 paper, 2023). A common cancer characterized by the presence of malignant glandular cells. "Notably, KCNQ4 demonstrated favorable prognosis in BRCA (0.37%), ESCA (1.65%), and LUAD (adenocarcinoma) (1.77%) with low mutation frequency, whereas it exhibited poor prognosis in UCEC with high mutation frequency (3.02%)." (PMID 37903775, 2023).
infection (1 paper, 2019). The state of being infected such as from the introduction of a foreign agent such as serum, vaccine, antigenic substance or organism. "KCNQ-type K+ channels composed of KCNQ2 and KCNQ4 may play a role in intestinal secretion and defense mechanisms in the case of infection and loss of epithelial integrity." (PMID 30250967, 2019).
KCNQ4 also shares sentences with these, for which no sentence is quoted: Hearing impairment (5 papers); Tinnitus (4); Onset (2); pulmonary hypertension (2); -Syndromic (1); allergic reaction (1); angina pectoris (1); Anxiety (1); asthma (1); autism (1); autoimmune disease (1); chronic obstructive pulmonary disease (1); colorectal cancer (1); depression (1); diabetes (1); diabetic polyneuropathy (1); encephalopathies (1); experimental autoimmune encephalomyelitis (1); genetic diseases (1); heart diseases (1); Hypokalemia (1); Intellectual disability (1); long QT syndrome (1); long QT syndrome type 1 (1); Menière's disease (1); migraine (1); neuromuscular disease (1); Noonan syndrome (1); overactive bladder syndrome (1); Pain (1).
A further 8 diseases each share a sentence with KCNQ4 in 1 paper.